PDCD6 (programmed cell death 6)
Diseases named in the same sentence as PDCD6 in open-access papers (continued):
Sharing a sentence is not in itself a finding about the gene and the disease.
colon cancer (3 papers, 2012 to 2020). "We next detected and analyzed the phosphorylation of p-MEK and the expression of the MAPK signal pathway downstream associated proteins to explore the correlation between PDCD6 and the MAPK pathway in colon cancer tissues." (PMID 32746883, 2020).
colorectal cancer (3 papers, 2020 to 2022). A primary or metastatic malignant neoplasm that affects the colon or rectum. "In this study, we investigated whether PDCD6 plays an oncogenic role in colorectal cancer and its underlying mechanism." (PMID 32746883, 2020). "High expression of PDCD6 was relevant to unfavorable prognosis in colorectal cancer patients via activating c-Raf, MEK and ERK pathway." (PMID 35503998, 2022). "Overexpression of PDCD6 was proved to promote the progression of colorectal cancer via cooperating with C-Raf and activating Raf/MEK/ERK signaling pathway." (PMID 33712026, 2021). "On the other hand, PDCD6 is also a Ca2+ binding protein, our results show that the PDCD6 play its role to promote cancer only when it combined with Ca2+, so we can also inhibit Ca2+ as targeting PDCD6 treatment project for the colorectal cancer patients." (PMID 32746883, 2020). "The functional experiments showed that PDCD6 depletion significantly inhibited colorectal cancer tumorigenesis and PDCD6 overexpression enhanced the proliferation and tumor growth of CRC cells." (PMID 32746883, 2020). "To investigate the PDCD6 function in colorectal cancer, we further generated stable PDCD6-knockdown (PDCD6-KD) HCT116 and HCT15 cell lines." (PMID 32746883, 2020). "In the present study, we explored the role of PDCD6 in the development and progression of colorectal cancer and the prognostic value of PDCD6 in patients with CRC." (PMID 32746883, 2020). "Statistical analysis showed that PDCD6 expression in colorectal cancer tissues was positively correlated with the pathological tumor-node-metastasis (pTNM) stages and pathological tumor (pT) stages, respectively." (PMID 32746883, 2020). "The Ca2 + −dependence can be excluded by the fact that Ca2+ is essential for the effect of PDCD6 on colorectal cancer." (PMID 32746883, 2020). "Overall, these observations indicated that targeting PDCD6 may provide a new opportunity for treating colorectal cancer." (PMID 32746883, 2020). "On one hand, PDCD6 could be used as a drug target for screening PDCD6 specific colorectal cancer treatment drug." (PMID 32746883, 2020). "The stabilized PDCD6/c-Raf complex subsequently activates the Raf/MEK/ERK signaling pathway and regulates the downstream transcription factors including MYC and JUN, which resulting in colorectal cancer growth and progression." (PMID 32746883, 2020). "However, the role of PDCD6 in the pathogenesis of colorectal cancer has not been thoroughly investigated." (PMID 32746883, 2020). "Furthermore, a Kaplan-Meier analysis revealed that PDCD6 overexpression in tumor cells had a significantly worse prognostic impact on the disease-free survival of patients with CRC, indicating that PDCD6 is a predictor of the survival of patients with colorectal cancer." (PMID 32746883, 2020).
lung adenocarcinoma (3 papers, 2012 to 2025). A carcinoma that arises from the lung and is characterized by the presence of malignant glandular epithelial cells. "The genes CEP72, BRD9, TRIP13, SLC9A3, SDHA, SLC6A19 and PDCD6 did not have any predictive role in lung adenocarcinoma prognosis." (PMID 26497366, 2015).
acute myeloid leukemia (1 paper, 2018). Acute myeloid leukemia (AML) is a group of neoplasms arising from precursor cells committed to the myeloid cell-line differentiation. "Furthermorem it has been proposed that miR-183 may function as an oncogene that may increase childhood acute myeloid leukemia (AML) cell proliferation by targeting PDCD6." (PMID 29872511, 2018).
B-cell NHL (1 paper, 2023).
cervical squamous cell carcinoma (1 paper, 2018). A squamous cell carcinoma arising from the cervical epithelium. "On the other hand, it has been revealed that rs3756712 and rs4957014 polymorphisms of PDCD6 significantly increased the risk of cervical squamous cell carcinoma (CSCC)." (PMID 29872511, 2018).
cyst (1 paper, 2018). A sac-like closed membranous structure that may be empty or contain fluid or amorphous material. "In immunofluorescence analysis, anti-Eg-Fis1 and anti-Eg-PDCD6 rabbit IgGs were applied for detection of their respective native proteins in adult worms, cyst walls (from fertile and infertile cysts), and PSCs in E. granulosus." (PMID 30205566, 2018).
left ventricular noncompaction (1 paper, 2023). Left ventricular noncompaction (LVNC) is a rare cardiomyopathy characterized anatomically by prominent left ventricular trabeculae and deep intratrabecular recesses causing progressive systolic and diastolic dysfunction, conduction abnormalities, and occasionally thromboembolic events. "Truncation and missense mutations have been observed in the repair protein AHNAK in congenital heart disease patients and a missense mutation in apoptosis-linked gene 2 (ALG-2, also called programmed cell death 6 protein [PDCD6]) is observed in patients with left ventricular noncompaction." (PMID 36728029, 2023).
nematode infection (1 paper, 2021). "Notably, the programmed cell death 6 (PDCD6) gene was downregulated as was the apoptosis pathway which suggests that maternal nematode infection might have downregulated apoptosis in the neonatal brain to further protect neural development." (PMID 34764345, 2021).
ovarian tumors (1 paper, 2012). "PDCD6 mRNA was detectable in most of ovarian tumor samples, and the expression was correlated with residual tumor size." (PMID 22369209, 2012).
virus infection (1 paper, 2020). "Our study firstly demonstrated the involvement of PDCD6 in the immune response of mud crabs on virus infection." (PMID 32597292, 2020). "In this study, the role of PDCD6 in virus infection was determined, the results showed that the upregulation of PDCD6 was found during the WSSV invasion, and the copy numbers of WSSV was increased in the PDCD6 silenced mud crabs." (PMID 32597292, 2020). "The results showed that Sp-PDCD6 contains five EF-hands domains and could suppress virus infection via apoptosis promotion." (PMID 32597292, 2020). "The results of this study revealed that miR-9875 could directly target PDCD6 and the miR-9875-PDCD6 pathway may regulate the apoptosis and virus infection in mud crab." (PMID 32597292, 2020). "In order to determine the effect of PDCD6 on virus infection, mud crabs were challenged with WSSV and the expression of PDCD6 was detected." (PMID 32597292, 2020). "So far, PDCD6 is known as a regulator in apoptosis, which is essential in the antiviral immunoregulation; however, the relationship between PDCD6 and virus infection in mud crab has not been previously addressed." (PMID 32597292, 2020). "However, the effects of miRNA-mediated regulation of PDCD6 expression on apoptosis and virus infection in organisms, especially in marine invertebrates, have not been extensively explored." (PMID 32597292, 2020).
cancer (29 papers, 2011 to 2025). A tumor composed of atypical neoplastic, often pleomorphic cells that invade other tissues. "Meanwhile, PDCD6 is also implicated in the development of cancer, but its role is controversial in different types of tumors." (PMID 33712026, 2021). "Remaining two genes implicated in UBC and NMIBC survival, namely EGFR and PDCD6, are both well-known cancer genes." (PMID 31681611, 2019). "The finding did not support an association between rs4957014 T>G polymorphism of PDCD6, and different cancers risk." (PMID 29872511, 2018). "The attained results suggest that the PDCD6 rs3756712 T>G polymorphism significantly decreased the risk of cancer under codominant, dominant, recessive, and allele genetic model." (PMID 29872511, 2018). "Previous studies inspecting the association between PDCD6 gene polymorphisms and cancer indicated inconclusive and contradictory results." (PMID 29872511, 2018). "Due to contrasting findings about PDCD6 polymorphism in certain types of cancers, the present meta-analysis was performed to evaluate the impact of two SNPs of PDCD6 on cancer risk." (PMID 29872511, 2018). "Several investigations have been done to find the possible association between two tag SNPs of PDCD6, rs3756712 and rs4957014 polymorphisms, and various cancer risk." (PMID 29872511, 2018). "In conclusion, to our knowledge, this fist the present study suggested that there is an association between the PDCD6 rs3756712 T>G polymorphism and cancer." (PMID 29872511, 2018). "The findings did not support an association between rs4957014 T>G polymorphism of PDCD6 and cancer risk." (PMID 29872511, 2018). "Hence, we have performed a meta-analysis on all the published case-control studies to evaluate the association of PDCD6 rs3756712 T>G and rs4957014 T>G gene polymorphisms with the risk of cancer." (PMID 29872511, 2018). "The association of mRNA expression of predicted target genes (PDCD6, GNG5, PHF6, MAL2, SLC25A15, PTDSS1) with clinicopathological parameters of BLCA patients were analyzed by UALCAN, containing BLCA individual cancer stages and molecular subtypes." (PMID 35503998, 2022). "Since the expression of PDCD6 changed most significantly in the three cancer cells and its function in HCC was still unclear, we selected it for further functional exploration." (PMID 33712026, 2021). "Previous studies have revealed that PDCD6 was involved in cancer development; The expression of PDCD6 varies in different tumors, indicating that PDCD6 plays different roles in different cancer types." (PMID 32746883, 2020). "De-regulation of PDCD6 gene expression has been reported in cancer cells and serves as a potential prognostic marker for certain types of cancer." (PMID 32878247, 2020). "And the inhibition of the knockdown of PDCD6 and c-Raf in combination was not further lower than the knockdown of c-Raf, which further confirmed that c-Raf was important and necessary in PDCD6 functions in promoting cancer progression." (PMID 32746883, 2020). "PDCD6 seems to be heavily involved in apoptosis; however, the exact role of PDCD6 is contrasting between various cancers, and further molecular research will help making evidence-based interpretations." (PMID 31681611, 2019). "This study was designed to evaluate the relationship between Programmed cell death protein 6 (PDCD6) polymorphisms and cancer susceptibility." (PMID 29872511, 2018). "In NSCLC, LncRNA PP7080 promotes the phosphorylation of TFAP2C, which then upregulates the expression of programmed cell death protein 6 (PDCD6) to promote cancer cell malignancy and to induce immune-suppressive tumor microenvironment by recruiting myeloid-derived suppressor cells." (PMID 37291585, 2023). "Furthermore, we performed a pan-cancer analysis of predicted target genes (PDCD6, GNG5, PHF6, MAL2, SLC25A15 and PTDSS1) by using TIMER." (PMID 35503998, 2022).
cancer (continued). "PDCD6, a member of the penta-EF-hand protein family, has been found to be dysregulated in the tumors of various origin and contributed to the viability of cancer cells." (PMID 32597292, 2020). "Inthis regard, miR-124-3p/PDCD6 signaling axis may be apotential target for treatment of patients with advancedbreast cancer." (PMID 31606975, 2020). "PDCD6 product participates in T-cell receptor-programmed cell death and may have a role in cancer survival pathways." (PMID 31139323, 2019). "Regarding rs4957014 T>G polymorphism of PDCD6, the finding did not support an association between rs4957014 T>G polymorphism and cancer risk." (PMID 29872511, 2018). "Moreover, recent studies indicate that PDCD6 has a synergic pro-apoptotic effect with anti-cancer drugs through the activation of NF-κB pathway." (PMID 24392146, 2014). "Programmed cell death 6 (PDCD6) beside its known proapoptotic functions may be a player in survival pathways in cancer." (PMID 22369209, 2012). "The activation of apoptotic genes like PDCD6, associated with apoptotic signalling cascades, and DDRGK1, implicated in DNA repair and apoptosis, suggests that fig latex triggers apoptosis pathways, leading to cell death specifically in HPV-positive cancer cells." (PMID 38139849, 2023). "Similarly, another paper showed miR-124 might serve as a tumor suppressor in malignant tumors, and thus, upregulated miR-124 could inhibit cell proliferation and migration by decreasing PDCD6 expression in SKOV3 and OCVAR3 cells." (PMID 34539736, 2021). "Multivariate analysis indicated that transcriptional expression of predicted target genes (PDCD6, GNG5, PHF6, MAL2, SLC25A15 and PTDSS1) were significantly correlated with BLCA individual cancer stages and molecular subtypes." (PMID 35503998, 2022). "However, in cancer cell lines, PDCD6 could mediate the inhibition of ASK1/JNK pathway through Raf-1 (Raf-1 protooncogene, serine/threonine kinase), thereby increasing tumor sensitivity to chemotherapy, and Raf-1 was required for MEK/2 activation under proapoptotic conditions." (PMID 36132985, 2022). "The result of qRT-PCR revealed that PDCD6, TCOF1 and FAM83D were highly expressed in HCC cancer cells." (PMID 33712026, 2021). "For the first time, our study reported that PDCD6 affects the MAPK signaling pathway in CRC, supplementing of the mechanistic investigation of PDCD6 in cancer." (PMID 32746883, 2020). "The expression level of programmed cell death 6 (PDCD6), a recently discovered pro-apoptotic protein, is down-regulated in cancer cell lines and OC tissues compared with that in normal cells and tissues." (PMID 29867465, 2018). "ALG-2 is associated with cancer development, and clinical investigation of cancer cells and tissues have revealed the usefulness of monitoring the expression of ALG-2 (often quoted PDCD6) as a biomarker for prognosis." (PMID 27571067, 2016). "Additionally, high transcriptional expression of PDCD6, GNG5, PHF6, MAL2, SLC25A15 and PTDSS1 were significantly correlated with BLCA individual cancer stages and molecular subtypes." (PMID 35503998, 2022). "High level of FSH could upregulate the expression of Survivin and suppress the expression of PDCD6 and DR5, thus to promote cancer development and inhibit cell apoptosis." (PMID 22768170, 2012). "Another PPI network GO analysis for PDCD6 and PDCDIP showed the vascular endothelial growth factor receptor-2 signaling pathway, negative regulation of the biological process, and negative regulation of phospholipase A2 activity which is related to cancer and other related diseases." (PMID 38283897, 2023).
tumor (17 papers, 2011 to 2025). "Higher expression levels of PDCD6 in tumor tissues were associated with a poorer prognosis in patients with CRC." (PMID 32746883, 2020). "Patients with medium or high levels of PDCD6 mRNA were at higher risk for disease progression, compared to those with low levels (HR, 1.29; P = 0.024 for mid levels; and HR, 1.57; P = 0.045 for high levels) after adjusting for age, disease stage, tumor grade, histologic type and residual tumor size." (PMID 22369209, 2012). "PDCD6 expression is known to increase in various tumor tissues like the lung, colon, breast, and ovary." (PMID 40365190, 2025). "Eight proteins were upregulated in the hippocampus in response to sustained tumour growth, including Psmd6, Rps28, calretinin (Calb2) and Pdcd6." (PMID 40172096, 2025). "By governing the AKT/GSK-3β pathway, PDCD6 emerges as a significant contributor to tumor progression in HCC." (PMID 39156976, 2024). "In summary, PDCD6 plays a pivotal role in promoting tumor growth in HCC, primarily through its modulation of the AKT/GSK-3β signaling pathway." (PMID 39156976, 2024). "A number of studies have been conducted to assess the expression levels of PDCD6 in tumor tissues and cell lines derived from clinical samples." (PMID 39156976, 2024). "miR-183 was reported to be up-regulated in BM and serum of pediatric AML and function tumor-promoting role by regulating programmed cell death 6 (PDCD6)." (PMID 37124518, 2023). "Results showed that both MAT2A and PDCD6 displayed an upregulated expression in tumor tissues compared with both normal tissue and adjacent normal tissues." (PMID 35396512, 2022). "To determine the effect of PDCD6 K90 methylation on tumor growth, we performed xenograft experiments using rPDCD6 WT and rPDCD6 K90R stable cell lines." (PMID 35396512, 2022). "We injected stable HCT116 and HCT15 stable cells into nude mice to explore the effect of PDCD6-OE on tumor growth in vivo." (PMID 32746883, 2020). "The roles of PDCD6 in cellular proliferation and tumor growth were measured by using CCK8, colony formation, and tumor xenograft in nude mice." (PMID 32746883, 2020). "Our study found that PDCD6 promotes tumor growth by interacting with c-Raf and regulating downstream the MAPK kinase pathway." (PMID 32746883, 2020). "The results show that the phosphorylation of p-MEK and the expression of MYC, JUN and PDCD6 were higher in tumor tissues than in adjacent normal tissues." (PMID 32746883, 2020). "HE staining revealed apparent tumor necrosis in the downregulated of PDCD6 compared with the control group, and the upregulated showed intense positive staining with smaller cell sizes and contracted nucleus." (PMID 32746883, 2020). "Collectively, these in vitro and in vivo experiments demonstrate that PDCD6 depletion significantly inhibits tumor cell growth." (PMID 32746883, 2020). "We injected HCT116 and HCT15 stable cells into nude mice to explore the effect of PDCD6-KD on tumor growth in vivo." (PMID 32746883, 2020). "The tumor-promoting activity of PDCD6 was characterized by in vitro and in vivo tumorigenesis assays." (PMID 32746883, 2020). "The tumor sizes and weights of the PDCD6-OE group xenografts were significantly greater than those of the vector control xenografts." (PMID 32746883, 2020). "The tumor sizes of the PDCD6-KD group xenografts were markedly smaller than those in the control group." (PMID 32746883, 2020). "Several studies have examined the expression of PDCD6 in clinical tumor tissues or cell lines, and found that PDCD6 has opposing effects in different tumors." (PMID 29872511, 2018). "PDCD6 also plays a significant role in modulating cellular angiogenesis and it can inhibit tumor growth via the suppression of tumor angiogenesis." (PMID 24392146, 2014). "Spearman correlation analysis showed PDCD6 expression was positively correlate with residual tumor size (r = 0.16, p = 0.019)." (PMID 22369209, 2012).